HLA-G (major histocompatibility complex, class I, G)
Description:
[Isoform 1]: Non-classical major histocompatibility class Ib molecule involved in immune regulatory processes at the maternal-fetal interface. In complex with B2M/beta-2 microglobulin binds a limited repertoire of nonamer self-peptides derived from intracellular proteins including histones and ribosomal proteins. Peptide-bound HLA-G-B2M complex acts as a ligand for inhibitory/activating KIR2DL4, LILRB1 and LILRB2 receptors on uterine immune cells to promote fetal development while maintaining maternal-fetal tolerance. Upon interaction with KIR2DL4 and LILRB1 receptors on decidual NK cells, it triggers NK cell senescence-associated secretory phenotype as a molecular switch to promote vascular remodeling and fetal growth in early pregnancy. Through interaction with KIR2DL4 receptor on decidual macrophages induces pro-inflammatory cytokine production mainly associated with tissue remodeling. Through interaction with LILRB2 receptor triggers differentiation of type 1 regulatory T cells and myeloid-derived suppressor cells, both of which actively maintain maternal-fetal tolerance. May play a role in balancing tolerance and antiviral-immunity at maternal-fetal interface by keeping in check the effector functions of NK, CD8+ T cells and B cells. Reprograms B cells toward an immune suppressive phenotype via LILRB1. May induce immune activation/suppression via intercellular membrane transfer (trogocytosis), likely enabling interaction with KIR2DL4, which resides mostly in endosomes. Through interaction with the inhibitory receptor CD160 on endothelial cells may control angiogenesis in immune privileged sites. [Isoform 2]: Likely does not bind B2M and presents peptides. Negatively regulates NK cell- and CD8+ T cell-mediated cytotoxicity. [Isoform 3]: Likely does not bind B2M and presents peptides. Negatively regulates NK cell- and CD8+ T cell-mediated cytotoxicity. [Isoform 4]: Likely does not bind B2M and presents peptides. Negatively regulates NK cell- and CD8+ T cell-mediated cytotoxicity. [Isoform 5]: Non-classical major histocompatibility class Ib molecule involved in immune regulatory processes at the maternal-fetal interface. In complex with B2M/beta-2 microglobulin binds a limited repertoire of nonamer self-peptides derived from intracellular proteins including histones and ribosomal proteins. Peptide-bound HLA-G-B2M complex acts as a ligand for inhibitory/activating KIR2DL4, LILRB1 and LILRB2 receptors on uterine immune cells to promote fetal development while maintaining maternal-fetal tolerance. Upon interaction with KIR2DL4 and LILRB1 receptors on decidual NK cells, it triggers NK cell senescence-associated secretory phenotype as a molecular switch to promote vascular remodeling and fetal growth in early pregnancy. Through interaction with KIR2DL4 receptor on decidual macrophages induces pro-inflammatory cytokine production mainly associated with tissue remodeling. Through interaction with LILRB2 receptor triggers differentiation of type 1 regulatory T cells and myeloid-derived suppressor cells, both of which actively maintain maternal-fetal tolerance. Reprograms B cells toward an immune suppressive phenotype via LILRB1. [Isoform 6]: Likely does not bind B2M and presents peptides. [Isoform 7]: Likely does not bind B2M and presents peptides.
Synonyms: MHC-G
Tractability: Small molecule: it has a high-quality binding pocket. Antibody: UniProt places it where antibodies can reach, with high confidence; its Gene Ontology location is reachable by antibodies, with high confidence; UniProt predicts a signal peptide or a membrane-spanning region. PROTAC: ubiquitination databases record sites on it.
Gene: Protein-coding gene on chromosome 6 (29,826,967 to 29,831,125, forward strand). Ensembl gene ENSG00000204632.
Subcellular location: Cell membrane (Isoform 1); Endoplasmic reticulum membrane; Early endosome membrane; Secreted (Soluble HLA class I histocompatibility antigen, alpha chain G); Cell membrane (Isoform 2); Cell membrane (Isoform 3); Cell membrane (Isoform 4); Secreted (Isoform 5); Early endosome; Secreted (Isoform 6); Secreted (Isoform 7); Cell projection, filopodium membrane
Pathways (Reactome):
Immune System: Antigen Presentation: Folding, assembly and peptide loading of class I MHC; ER-Phagosome pathway; Endosomal/Vacuolar pathway; Immunoregulatory interactions between a Lymphoid and a non-Lymphoid cell; Interferon alpha/beta signaling; Interferon gamma signaling
Disease: SARS-CoV-2 activates/modulates innate and adaptive immune responses
Gene Ontology:
Molecular function: CD8 receptor binding; identical protein binding; peptide antigen binding; protein binding; protein homodimerization activity; signaling receptor binding; beta-2-microglobulin binding
Biological process: antigen processing and presentation of endogenous peptide antigen via MHC class Ib; antigen processing and presentation of exogenous peptide antigen via MHC class Ib; immune response-inhibiting cell surface receptor signaling pathway; negative regulation of angiogenesis; negative regulation of dendritic cell differentiation; negative regulation of G0 to G1 transition; negative regulation of natural killer cell mediated cytotoxicity; negative regulation of phosphatidylinositol 3-kinase/protein kinase B signal transduction; negative regulation of T cell mediated cytotoxicity; negative regulation of T cell proliferation; peripheral B cell tolerance induction; positive regulation of cellular senescence; positive regulation of endothelial cell apoptotic process; positive regulation of interleukin-12 production; positive regulation of macrophage cytokine production; positive regulation of natural killer cell cytokine production; positive regulation of regulatory T cell differentiation; positive regulation of T cell tolerance induction; positive regulation of tolerance induction; protection from natural killer cell mediated cytotoxicity; protein homotrimerization; antigen processing and presentation of endogenous peptide antigen via MHC class I via ER pathway, TAP-independent; cellular defense response; immune response; negative regulation of immune response; and 2 more
Cellular component: cis-Golgi network membrane; early endosome; early endosome membrane; endoplasmic reticulum membrane; extracellular region; membrane; MHC class Ib protein complex; plasma membrane; ER to Golgi transport vesicle membrane; external side of plasma membrane; Golgi membrane; lumenal side of endoplasmic reticulum membrane; phagocytic vesicle membrane; recycling endosome membrane; filopodium membrane
Genetic constraint (gnomAD): Loss-of-function variants: 34 observed, 39.67 expected, observed/expected ratio (o/e) 0.86, 90% interval 0.65 to 1.14. The upper end of that interval is the gene's LOEUF score, 1.14, which puts it in group 5 of 6, group 1 being the genes least tolerant of losing a copy. Missense variants: 419 observed, 459.79 expected, observed/expected ratio (o/e) 0.91, 90% interval 0.84 to 0.99. Synonymous variants: 183 observed, 186.64 expected, observed/expected ratio (o/e) 0.98, 90% interval 0.87 to 1.11.
Homologues: Orthologues: chimpanzee PATR-G (99% identical), zebrafish si:ch211-147g22.4 (17% identical), zebrafish mhc1lia (14% identical). Paralogues in human: HLA-A (83% identical), HLA-B (81% identical), HLA-C (80% identical), HLA-F (78% identical), HLA-E (76% identical), HFE (36% identical), MR1 (36% identical), AZGP1 (30% identical), MICB (27% identical), MICA (26% identical), FCGRT (26% identical), CD1A (24% identical), and 10 more.
Diseases named in the same sentence as HLA-G in open-access papers:
HLA-G is named in the same sentence as 337 diseases in open-access papers, as found by Europe PMC text mining. Sharing a sentence is not in itself a finding about the gene and the disease. The quoted sentences say what the papers report.
breast carcinoma (73 papers, 2008 to 2025). "In breast cancer, HLA-G + 3142G was a protective factor for cancer susceptibility, while the + 3142C allele acted in the opposite way." (PMID 38310272, 2024). "HLA-G is associated with the tumor-driven immune escape mechanism in the advanced stages of breast cancer." (PMID 38476263, 2024). "Several studies have shown that the expression of HLA-G is significantly associated with progression and poor prognosis in a variety of tumors including aggressive breast carcinoma." (PMID 35185887, 2022). "Five studies reported on the association between HLA-G tumour expression and clinical outcome of breast carcinoma patients." (PMID 34361031, 2021). "A concomitant loss of HLA class Ia and high expression of HLA-G and HLA-E is associated with a worse prognosis and increased metastatic capacity in breast cancer." (PMID 32560316, 2020). "For early breast cancer patients with loss of classical HLA class I expression, expression of HLA-G resulted in a worse relapse-free period." (PMID 33425752, 2020). "Breast cancer cells also express HLA-G, and HLA-G expression in breast cancers is associated with poor prognosis." (PMID 32023940, 2020). "High levels of HLA‐G+ TDEs in peripheral blood samples of breast cancer patients receiving neoadjuvant chemotherapy were also associated with disease progression, whereas high levels of soluble HLA‐G were associated with improved clinical outcomes." (PMID 31318078, 2020). "The aim of this study was to determine the possible associations of soluble HLA-G and HLA-G +3142G/C SNP with breast cancer." (PMID 31759373, 2019). "HLA-G alleles were determined by direct DNA sequencing procedures from blood samples of 80 breast cancer patients and 80 healthy controls." (PMID 24870375, 2014). "The presence of 14-bp of HLA-G was associated with breast cancer susceptibility according to the results of HLA-G expression in tissue." (PMID 24870375, 2014). "The presence of HLA-G 3′ untranslated region (UTR) 14-bp sequence was analyzed and found to be associated with reduced risk of breast cancer susceptibility based on HLA-G expression in tissues (P = 0.0407)." (PMID 24870375, 2014). "Studies have found that high expression of HLA-G is associated with breast cancer metastasis." (PMID 38427106, 2024). "Furthermore, in breast cancer, the interaction between HLA-G and the NK cell receptor KIR2DL4 amplifies the susceptibility of HER2-positive breast cancer cells to trastuzumab, elucidating the mechanisms underlying the resistance to trastuzumab." (PMID 38283362, 2023). "HLA-G expression was also associated with subtypes of breast cancer." (PMID 35185887, 2022). "This shows, HLA-G associates in many respects with poor clinical outcome in breast carcinomas." (PMID 34361031, 2021). "The aim of this study was to investigate whether sHLA-G level and HLA-G +3142G/C SNP are associated with breast cancer in Tanzanian patients." (PMID 31759373, 2019). "Moreover, high levels of HLA-G-bearing EVs were observed to be positively associated with disease progression in advanced breast cancer patients undergoing neoadjuvant chemotherapy." (PMID 30319626, 2018). "HLA-G seems to be implicated in the immune escape mechanisms of breast cancer." (PMID 24870375, 2014). "Furthermore, HLA-G expression in breast cancer lesions was significantly associated with the homozygous presence of 14-bp, with a P-value of 0.0407." (PMID 24870375, 2014). "In addition, the association between HLA-G polymorphism and expression was analyzed in the same patient population to investigate the possible mechanism of HLA-G in breast carcinoma." (PMID 24870375, 2014). "HLA-G polymorphism and expression may be involved in breast carcinogenesis and sHLA-G concentrations could be used as a diagnostic marker for detecting breast cancer." (PMID 24870375, 2014).
breast carcinoma (continued). "In addition, it is also necessary to unravel the mechanisms underlying HLA-G/KIR2DL4 regulation of the immune microenvironment in breast cancer, hopefully providing a rationale for combined HLA-G and immune checkpoints targeting for the effective treatment of breast cancer." (PMID 35185887, 2022). "However, it remains largely unclear whether HLA-G-bearing EVs are produced by tumor cells, while there is a functional association between the HLA-G-bearing EVs and various tumors, such as melanoma, breast cancer, and kidney cancer." (PMID 34868081, 2021). "Thus, human mast cells are associated with an invasive phenotype of HLA-G-positive breast cancers." (PMID 32023940, 2020). "Therefore, the 14-bp HLA-G gene polymorphism could be involved in breast carcinogenesis, and the measurement of sHLA-G concentrations have diagnostic value for detecting breast cancer and metastasis." (PMID 24870375, 2014). "A recent study demonstrated that KIR2DL4 synergized with FcRγ to augment NK cell activation and degranulation, whereas the interaction of HLA-G with KIR2DL4 attenuated NK cell cytotoxicity in HER2-positive breast cancer." (PMID 38310272, 2024). "Experimental studies suggest that disrupting the HLA-G/KIR2DL4 pathway can enhance the immune response of NK cells against breast cancer cells, thereby improving trastuzumab’s anti-tumor effect." (PMID 39655080, 2024). "Trastuzumab responsiveness for HER2-positive breast cancer can be improved by blocking the HLA-G/KIR2DL4 signaling pathway." (PMID 37981615, 2024). "We previously found that breast cancer cells express HLA-G, which inhibits the cytotoxicity of NK cells by binding to the receptor KIR2DL4." (PMID 37981615, 2024). "In breast cancer cells that exhibit high HLA-G expression, binding to KIR2DL4 on natural killer (NK) cells suppresses their anti-tumor activity, thereby reducing the therapeutic efficacy of trastuzumab." (PMID 39655080, 2024). "HLA-G and PD-L1 exhibited consistent high-expression in pancreatic cancer, breast cancer, papillary thyroid cancer, kidney cancer, colorectal cancer, oral osteosarcomas, and intraoral mucoepidermoid carcinoma." (PMID 38310272, 2024). "The expression of HLA-G was upregulated in breast cancer and malignant melanoma was found, which was partially regulated by DNA methylation." (PMID 38427106, 2024). "HRAS gene showed a hazard ratio (HR) = 9.53 (95% CI: 1.3–69.88) and log-rank p-value = 0.006 for breast cancer; indicating that the result was statistically significant (the relation between the high expression of HLA-G gene and greater survival rate)." (PMID 36358305, 2022). "Our recent study has showed that human leukocyte antigen-G (HLA-G) was a pivotal mediator of HER2 positive breast cancer resistance to trastuzumab and blockade of HLA-G can improve the antitumor activity of NK cells significantly." (PMID 35185887, 2022). "A better understanding of HLA-G is beneficial to identifying novel biomarker(s) for breast cancer, which is important for precision diagnosis and prognostic assessment." (PMID 35185887, 2022). "Our previous study had shown that HLA-G was a pivotal mediator of breast cancer resistance to trastuzumab, and blockade of the HLA-G/KIR2DL4 interaction can resensitize breast cancer to trastuzumab treatment." (PMID 35185887, 2022). "HLA-G is an inhibitory checkpoint molecule, which is highly expressed in gynecological cancers, such as cervical cancer, ovarian cancer, breast cancer, and endometrial cancer." (PMID 36618382, 2022). "In 2003, a comparative study reported that soluble HLA-G can be detected in the malignant ascites of breast cancer patients." (PMID 35185887, 2022). "Zhang’s team reported that overexpression of HLA-G in breast cancer cells was induced by abnormal DNA methylation modification, which was mediated by DNA methyltransferase (DNMT) and ten-eleven translocation (TET)." (PMID 35185887, 2022).
breast carcinoma (continued). "In breast cancer immune microenvironment, HLA-G can bind to its receptor, such as KIR2DL4, to induce immunosuppression." (PMID 35185887, 2022). "In 2010, a comparative study reported that estradiol/progesterone-induced HLA-G expression can inhibit allo-cytotoxic lymphocyte response to human breast cancer MCF-7 cells." (PMID 35185887, 2022). "In this review, we aim to summarize and discuss the role of HLA-G/KIR2DL4 in the immune microenvironment of breast cancer." (PMID 35185887, 2022). "In this review, we aim to summarize the roles of HLA-G/KIR2DL4 in breast cancer immune microenvironment." (PMID 35185887, 2022). "Our recent study has showed that HLA-G can desensitize breast cancer cells to trastuzumab by binding to the NK cell receptor KIR2DL4." (PMID 35185887, 2022). "Recently, we have found that HLA-G expression can predict a low trastuzumab response in HER2 positive breast cancer patients." (PMID 35185887, 2022). "Together, these findings suggest the necessity of combined HLA-G and PD-L1/PD-1 targeting for the effective treatment of trastuzumab-resistant breast cancer." (PMID 34158475, 2021). "Blocking HLA-G or KIR2DL4 also promoted trastuzumab-induced degranulation of NK cells cocultured with HER2-positive breast cancer cells." (PMID 34158475, 2021). "More importantly, another study involving 30 patients revealed that breast cancer expressing higher HLA-G exhibited lower response rates to trastuzumab treatment." (PMID 34158475, 2021). "In patients with breast cancer, the expression of HLA-G is negatively correlated with proliferation factor." (PMID 34868081, 2021). "Genetic deletion of ADAM17 in leukocytes leads to later onset of breast cancer growth, while HLA-G is produced by tumor-infiltrating microglia in most glioblastomas." (PMID 33971970, 2021). "Clinical breast cancers that express higher levels of HLA-G had a poorer prognosis and a higher probability of recurrence in patients." (PMID 34158475, 2021). "Blockade of HLA-G/KIR2DL4 signaling improved the vulnerability of HER2-positive breast cancer to trastuzumab treatment in vivo." (PMID 34158475, 2021). "The development of trastuzumab resistance was coordinated by a remarkable upregulation of HLA-G as observed in clinical HER2-positive breast cancer samples." (PMID 34158475, 2021). "The present study demonstrate two different approaches to manipulate HLA expression in an in vitro breast cancer and malignant melanoma setting and support a role for DNA methylation in regulation of HLA-G expression." (PMID 32560316, 2020). "The aim of this study was to evaluate the prognostic and predictive value of HLA-G and HLA-F protein isoform expression patterns in patients with breast cancer." (PMID 32978482, 2020). "HLA-G gene in breast cancer had a hazard ratio (HR) = 0.85 (95% CI, 0.69–1.06) and logrank p-value = 0.15; therefore the result was not statistically significant (HLA-G deregulation had not the prognostic value)." (PMID 32867672, 2020). "A detailed molecular investigation of HLA-G and its regulation in an in vitro breast cancer or malignant melanoma setting will contribute to the search of mechanisms that can be exploited to therapeutically target HLA-G-mediated immune suppression in cancer." (PMID 32560316, 2020). "It is reported that human leukocyte antigen G (HLA-G) can make tumor escape immune surveillance and is highly expressed in a variety of tumors, such as gastric cancer, renal cell carcinoma, and breast cancer 25-27." (PMID 32913475, 2020). "The primary aim of the study was therefore to analyse the distribution of HLA-G and HLA-F across the molecular subgroups of breast cancer." (PMID 32978482, 2020). "In contrast to the present study, they used an enzyme-linked immunosorbent assay (ELISA) to measure HLA-G5/G6 together in vesicular-derived soluble HLA-G, as well as total soluble HLA-G serum levels in breast cancer patients before and after NACT." (PMID 32978482, 2020).